MXRA5 (matrix remodeling associated 5)
Diseases named in the same sentence as MXRA5 in open-access papers (continued):
Sharing a sentence is not in itself a finding about the gene and the disease.
pancreatic cancer (continued). "Bioinformatics studies and the protein chip analyses revealed that differentially expressed genes (DEGs) and differentially expressed proteins (DEPs) in MXRA5-overexpressed primary pancreatic cancer cells were enriched in the PI3K-Akt-mTOR cascade." (PMID 36828810, 2023). "Contrarily, ectopic overexpression of MXRA5 accelerated growth and migration of pancreatic cancer cells." (PMID 36828810, 2023). "Results again show that MXRA5 expression is remarkably elevated in pancreatic cancer (PAAD) tissues (blue box), while its expression is relative low in normal pancreatic tissues." (PMID 36828810, 2023). "MXRA5 overexpression in pancreatic cancer was correlated with higher T classification (AUC = 0.659), N classification (AUC = 0.640) and clinical pathological stage (AUC = 0.712)." (PMID 36828810, 2023). "Conversely, forced overexpression of MXRA5 further promoted pancreatic cancer cell progression and EMT." (PMID 36828810, 2023). "Bioinformatics studies revealed that MXRA5 transcripts are significantly elevated in pancreatic cancer tissues, correlating with the poor overall survival, high T-stage, N1 and pathologic stage of the patients." (PMID 36828810, 2023). "MXRA5 protein upregulation was also detected in pancreatic cancer tissues of six representative patients (“Patient 1#” and “Patient 6#”)." (PMID 36828810, 2023). "Together, overexpressed MXRA5 is important for pancreatic cancer cell growth possibly through promoting EMT and Akt-mTOR activation." (PMID 36828810, 2023). "As shown, MXRA5 mRNA and protein expression in different pancreatic cancer cells was significantly elevated when compared to its expression in pEpi cells." (PMID 36828810, 2023). "At last, we tested whether MXRA5 silencing could inhibit primary pancreatic cancer cell growth in vivo." (PMID 36828810, 2023). "We here propose that overexpressed MXRA5 could be an important protein for pancreatic cancer progression, representing as a promising therapeutic target." (PMID 36828810, 2023). "Elevated MXRA5 gene expression has been demonstrated in pancreatic cancer." (PMID 37511632, 2023). "We next hypothesized that ectopic overexpression of MXRA5 could possibly exert pro-cancerous activity in pancreatic cancer cells." (PMID 36828810, 2023). "Contrarily MXRA5 overexpression promoted primary pancreatic cancer cell growth in nude mice." (PMID 36828810, 2023). "In addition, Akt-mTOR activation was also largely inhibited in the MXRA5-depleted pancreatic cancer xenografts." (PMID 36828810, 2023). "Indeed, Akt-mTOR activation was largely inhibited by MXRA5 shRNA or knockout in primary pancreatic cancer cells, but was augmented following ectopic overexpression of MXRA5." (PMID 36828810, 2023). "Our results revealed that MXRA5 was important for the migration and invasion of pancreatic cancer cells, it therefore could possibly influence EMT." (PMID 36828810, 2023). "The expression of MXRA5 in human pancreatic cancer cells was studied." (PMID 36828810, 2023). "Therefore, intratumoral injection of MXRA5 shRNA virus remarkably hindered primary pancreatic cancer xenograft growth in vivo." (PMID 36828810, 2023). "These bioinformatics studies confirmed elevated MXRA5 expression in human pancreatic cancer." (PMID 36828810, 2023). "The receiver operating characteristic (ROC) curve results imply that MXRA5 overexpression could have a potential predictive value on the 1-/3-/5-year survival of pancreatic cancer patients." (PMID 36828810, 2023). "Moreover, intratumoral injection of aav-packed MXRA5 shRNA potently inhibited primary pancreatic cancer cell growth in nude mice." (PMID 36828810, 2023). "Indeed, Akt-mTOR activation in primary human pancreatic cancer cells was inhibited by MXRA5 shRNA or knockout, but was augmented following MXRA5 overexpression." (PMID 36828810, 2023). "Thus, MXRA5-driven pancreatic cancer cell growth is possibly due to, at least in part, by promoting Akt-mTOR signaling." (PMID 36828810, 2023).
pancreatic cancer (continued). "Akt-mTOR activation was also largely inhibited in the MXRA5-depleted pancreatic cancer xenografts." (PMID 36828810, 2023). "Here we revealed that MXRA5 could be a novel and important oncogenic gene for pancreatic cancer." (PMID 36828810, 2023). "We tested whether MXRA5 is important for FAK activation in pancreatic cancer cells." (PMID 36828810, 2023). "Therefore MXRA5 is important for Akt-mTOR activation in pancreatic cancer cells." (PMID 36828810, 2023). "MXRA5 could be a potential therapeutic oncotarget for pancreatic cancer." (PMID 36828810, 2023). "Therefore, MXRA5 could be an important therapeutic oncotarget of pancreatic cancer." (PMID 36828810, 2023). "In primary and immortalized (BxPC-3 and PANC-1 lines) pancreatic cancer cells, shRNA-induced MXRA5 silencing or CRISPR/Cas9-mediated MXRA5 knockout suppressed cell survival, proliferation, migration, invasion, and epithelial-mesenchymal transition (EMT), while provoking cell apoptosis." (PMID 36828810, 2023). "Moreover, MXRA5’s expression and biological functions in human pancreatic cancer have not been studied yet." (PMID 36828810, 2023).
preeclampsia (3 papers, 2020 to 2022). Preeclampsia is a hypertensive disorder of pregnancy that is characterized by new-onset hypertension with proteinuria presenting after 20 weeks of gestation, and depending on mild or severe forms may initially present with severe headache, visual disturbances, and hyperreflexia. "MXRA5 has been associated with several diseases and conditions, including preeclampsia and colorectal cancer." (PMID 36513788, 2022). "Interestingly, a recent study reported that the MXRA5 protein is a positive regulator of the MAPK signaling pathway in preeclampsia." (PMID 32392178, 2020).
adenoma (2 papers, 2013 to 2022). A neoplasm arising from the epithelium. "Notably, MXRA5 protein expression was also detected in human adenoma tissues in our study, and the protein expression level of MXRA5 from normal colorectal to adenoma and then to carcinoma tissue markedly increased, paralleling the increasing severity of colorectal tissue injury." (PMID 23420087, 2013). "There was a significant difference in MXRA5 expression in CRC tissues and adenoma tissues compared with normal tissues." (PMID 23420087, 2013).
colorectal adenocarcinoma (2 papers, 2021 to 2024). The most common type of colorectal carcinoma. "Differential gene expression analysis showed distinct gene expression patterns in GCA compared to colorectal adenocarcinoma, with a number of cancer-related differentially expressed genes, including upregulation of TMEM14A, GOLT1A, DSCC1, and HSD17B8, and downregulation of KCNQ1OT1 and MXRA5." (PMID 34804955, 2021).
kidney cancer (2 papers, 2017 to 2020). Primary or metastatic malignant neoplasm involving the kidney. "We then explored factors regulating MXRA5 expression and MXRA5 function in cultured human proximal tubular epithelial cells and explored MXRA5 expression in kidney cancer cells and kidney tissue." (PMID 27599751, 2017). "MXRA5 has also been described to be a promising marker of early tissue injury and fibrosis, and its application has been extensively investigated in experimental studies of myocardial damage, kidney cancer, and chronic kidney disease." (PMID 32984216, 2020).
kidney damage (2 papers, 2017 to 2020). "Urine MXRA5 concentrations may provide a sensitive marker of early kidney damage in children with UPJO-induced hydronephrosis and there may be a relationship between MXRA5 concentration and disease severity." (PMID 32984216, 2020). "After observing an up‐regulation of MXAR5 expression in human nephropathies characterized by kidney inflammation and fibrosis, we explored the potential regulation of MXRA5 expression by a representative fibrogenic cytokine TGFβ1 and a representative pro‐inflammatory cytokine, TWEAK." (PMID 27599751, 2017).
lung adenocarcinoma (2 papers, 2020). A carcinoma that arises from the lung and is characterized by the presence of malignant glandular epithelial cells. "Six genes (COL3A1, COL1A2, OGN, COL15A1, ASPN, and MXRA5) and three miRNAs (hsa-miR-29c-3p, hsa-let-7c-5p, and hsa-miR-29b-3p) were related to the survival time of lung adenocarcinoma (LUAD)." (PMID 32300359, 2020).
autosomal dominant polycystic kidney disease (1 paper, 2017). Autosomal dominant form of polycystic kidney disease. "Furthermore, MXRA5 mRNA expression was increased in cysts from autosomal dominant polycystic kidney disease (ADPKD) patients and expression was localized to cyst lining tubular cells by immunohistochemistry." (PMID 27599751, 2017).
chronic kidney disease (1 paper, 2020). Impairment of the renal function secondary to chronic kidney damage persisting for three or more months. "Recent investigations have described the use of urinary matrix remodeling-associated protein 5 (MXRA5) as a novel biomarker of kidney impairment in the setting of chronic kidney disease." (PMID 32984216, 2020). "The highest levels of MXRA5 have been detected in the kidney, and high tubular cell expression of MXRA5 was recently identified in human chronic kidney disease tissue." (PMID 32984216, 2020).
clear cell renal carcinoma (1 paper, 2017). A malignant epithelial neoplasm of the kidney characterized by the presence of lipid-containing clear cells within a vascular network. "Furthermore, in clear cell renal cancer, von Hippel–Lindau (VHL) regulated MXRA5 expression." (PMID 27599751, 2017).
colorectal adenoma (1 paper, 2013). An adenoma that arises from the colon or rectum. "The MXRA5 expression levels were determined by quantitative real-time PCR (qRT-PCR) and immunohistochemistry (IHC) in 20 colorectal adenoma tissues, 156 CRC tissues and their corresponding adjacent normal mucosa." (PMID 23420087, 2013).
colorectal tumor (1 paper, 2021). "It is, however, interesting to note that MXRA5 was shown to be aberrantly expressed in colorectal tumor tissue." (PMID 33919912, 2021).
Crohn disease (1 paper, 2025). A gastrointestinal disorder characterized by chronic inflammation involving all layers of the intestinal wall, noncaseating granulomas affecting the intestinal wall and regional lymph nodes, and transmural fibrosis. "After adjusting for potential confounders, multivariate analysis identified serum MXRA5 levels (OR = 1.018, 95 % CI 1.003–1.034) and perianal lesions (OR = 0.169, 95 % CI 0.029–0.971) as predictors of endoscopic response at week 24 in Crohn's Disease patients receiving IFX therapy." (PMID 40688463, 2025).
disc degeneration (1 paper, 2021). "DDK3 and MXRA5 were also upregulated in Pro NPC and Adh NPC, suggesting that the cell metabolic homeostasis exists in different cell subtypes during disc degeneration." (PMID 35295968, 2021).
hydronephrosis (1 paper, 2020). Collection of urine in the renal pelvis that results in dilatation of the renal pelvis and calyces. "Second, MXRA5 levels were not measured after hydronephrosis had improved, and it would be helpful to assess the relationship between MXRA5 level and clinical end-points during follow up." (PMID 32984216, 2020).
Intellectual disability (1 paper, 2017). "Examples include SUMF1, KDM5B and MXRA5 (Known-ASD genes), PRODH2 and KCTD21 (implicated in schizophrenia), as well as USP9X and SMS (implicated in intellectual disability)." (PMID 28720891, 2017).
kidney injury (1 paper, 2020). Trauma to the kidney. "Our results indicate that MXRA5 in urine exosomes has potential utility in the diagnosis of UPJO-induced kidney injury." (PMID 32984216, 2020). "The present results show that MXRA5 in urinary exosomes is more strongly correlated with UPJO than whole-urine MXRA5, which implies it may be useful for the identification of UPJO-induced kidney injury." (PMID 32984216, 2020).
malignant pleural mesothelioma (1 paper, 2022). A malignant neoplasm that arises from mesothelial cells in the pleura and shows a diffuse growth pattern. "Patients with malignant pleural mesothelioma and a high MXRA5 mutation frequency have a longer survival time." (PMID 35292033, 2022).
Obesity (1 paper, 2026). Accumulation of substantial excess body fat. "RESULTS: F2R and MXRA5 were identified as core YAP/TAZ-effector genes associated with obesity and BRCA." (PMID 41968212, 2026).
pterygium (1 paper, 2021). A wedge-shaped fibrovascular lesion arising from the bulbar conjunctiva and extending to the cornea. "Interestingly, the high expression of MXRA5 in our study suggests that it may remodel the ECM by activating TGFβ in pterygium." (PMID 34249924, 2021). "Using GEO databases, we also identified five hub genes (DSP, MXRA5, ARHGAP35, TMEM43, and OLFML2A) that were most correlated with the development of pterygium." (PMID 34249924, 2021). "After analyzing the differentially methylated m6A peaks and synchronously differentially expressed genes, we searched the Gene Expression Omnibus database and identified five genes related to the development of pterygium (DSP, MXRA5, ARHGAP35, TMEM43, and OLFML2A)." (PMID 34249924, 2021).
renal carcinoma (1 paper, 2017). A carcinoma arising from the epithelium of the renal parenchyma or the renal pelvis. "We then studied MXRA5 expression in renal biopsies from renal carcinoma patients." (PMID 27599751, 2017).
serous ovarian cancer (1 paper, 2024).
vasculitis (1 paper, 2020). "Evidence for association has previously been identified between MXRA5 and antineutrophil cytoplasmic antibody (ANCA)-associated vasculitis, which can be associated with severe ocular inflammatory disease and loss of vision." (PMID 32926103, 2020).
cancer (26 papers, 2007 to 2025). A tumor composed of atypical neoplastic, often pleomorphic cells that invade other tissues. "The 5 members of the M0-ECM signature, FN1, VCAN, COL11A1, SFRP2, and MXRA5, have been associated with cancer progression, through markers of prognosis or the process of metastasis." (PMID 37188691, 2023). "Matrix remodeling associated 5 (MXRA5) was a novel extracellular protein that was also up-regulated in several types of cancers." (PMID 35752862, 2022). "The lentiviral particles encoding MXRA5 cDNA were added to priPC-1 primary cancer cells." (PMID 36828810, 2023). "The potential function of MXRA5 in human cancer and its underlying mechanisms are largely unknown." (PMID 36828810, 2023). "Conversely, shRNA-induced knockdown or CRISPR/Cas9-induced knockout of MXRA5 suppressed the phosphorylations of Akt (Ser-473) and S6 in priPC-1 primary cancer cells." (PMID 36828810, 2023). "To determine the expression of MXRA5 in cancer cells, we evaluated MXRA5 expression in the CCLE with 1019 cancer cell lines." (PMID 34211612, 2021). "MXRA5, a secreted glycoprotein, is involved in cell adhesion and extracellular matrix remodeling and has been reported to be expressed in many cancers." (PMID 34211612, 2021). "Studies have shown that MXRA5 also plays an important role in the development and progression of cancers." (PMID 34211612, 2021). "Lastly, some genes (HMGN5, IRS1, PHGDH, MXRA5, GOLIM4, and SFRP2) are associated with the development of multiple cancer types." (PMID 33924951, 2021). "In other cancers, MXRA5 has also been shown to be a cancer-promoting gene." (PMID 40002669, 2025). "However, it failed to affect pEpi cell proliferation (EdU incorporation) and CCK-8 viability, supporting a cancer cell-specific effect by MXRA5 silencing." (PMID 36828810, 2023). "Indeed, ectopic overexpression of MXRA5 in priPC-1 primary cancer cells increased phosphorylation of Akt (Ser-473) and S6." (PMID 36828810, 2023). "Whereas in the primary human pancreatic epithelial cells (“pEpi”), ectopic MXRA5 overexpression by the same method failed significantly increase cell viability and proliferation (EdU incorporation), again supporting a cancer cell-specific effect by MXRA5." (PMID 36828810, 2023). "Our driver selection method successfully identified 116 probable novel cancer-causing genes, with 4 discovered in patients having no alterations in any known driver genes: MXRA5, OBSCN, RYR1, and TG." (PMID 33232371, 2020). "The upregulation of gene products associated with migration and invasion (osteopontin, MMP1, vimentin, filamin-A, and β-actin) and gene products for extracellular matrix molecules and their modulators (fibronectin, collagen, ITGBL1, and MXRA5) reflects the invasive nature of this cancer." (PMID 25861239, 2015). "Our results further show that VHL may be a driver of MXRA5 expression in cancer cells." (PMID 27599751, 2017). "We determined gene expression in nine cancerous and tumor- adjacent tissues from patients with GBM and found that expression levels of FMOD, MXRA5, and RAB36 in the cancer tissue was higher than those in the para-cancerous tissue in most patients." (PMID 39513108, 2024). "Conversely, in both priPC-1 primary cancer cells and established PANC-1 cells, shRNA-mediated knockdown or CRISPR/Cas9-induced knockout of MXRA5 exerted opposite functions by upregulating E-Cadherin, but downregulating N-Cadherin and vimentin." (PMID 36828810, 2023). "To determine the subcellular localization of MXRA5, we performed IF staining with A172 and TJ905 cancer cells." (PMID 34211612, 2021).